AGO2 (argonaute RISC catalytic component 2)
Diseases named in the same sentence as AGO2 in open-access papers (continued):
Sharing a sentence is not in itself a finding about the gene and the disease.
Hodgkins lymphoma (3 papers, 2014 to 2017). A heterogeneous group of malignant lymphoid neoplasms of B-cell origin characterized histologically by the presence of Hodgkin and Reed-Sternberg (HRS) cells in the vast majority of cases. "We analyzed the short RNAs from immunoprecipitated Ago1 and Ago2 proteins isolated from L591cells derived from EBV-positive Hodgkin’s lymphoma cells." (PMID 24627180, 2014).
Huntington disease (3 papers, 2017 to 2022). Huntington disease (HD) is a rare neurodegenerative disorder of the central nervous system characterized by unwanted choreatic movements, behavioral and psychiatric disturbances and dementia. "In mouse models, as well as in post-mortem material from patients with Huntington’s Disease (HD), AGO2 accumulation is observed when neuronal protein aggregates are formed, as a result of impaired autophagy." (PMID 32503341, 2020).
Intellectual disability (3 papers, 2023 to 2025). "All four intellectual disability individuals carried the novel AGO2 (NM_012154.5): c.2149T>C (p.Cys717Arg) variant, while the other individuals did not." (PMID 40574801, 2025). "Taking into account the mode of inheritance and the clinical phenotype, we preliminarily consider the AGO2 (NM_012154.5): c.2149T>C (p.Cys717Arg) variant to be the likely cause of the proband’s intellectual disability." (PMID 40574801, 2025). "Our findings expand the variants spectrum of AGO2 leading to LESKRES and highlight the value of WES in diagnosing genetic causes of intellectual disabilities." (PMID 40574801, 2025). "AGO2 (MIM*606229) variants lead to LESKRES (MIM #619149), an autosomal dominant disorder, with symptoms including global developmental delay, intellectual disability, and delays in speech and language development." (PMID 40574801, 2025).
lung adenocarcinoma (3 papers, 2014 to 2024). A carcinoma that arises from the lung and is characterized by the presence of malignant glandular epithelial cells. "Moreover, analyses of AGO2 protein levels in the public database of Clinical Proteomic Tumor Analysis Consortium (CPTAC) revealed a decrease in both lung adenocarcinoma (n = 111) and lung squamous cell carcinoma samples (n = 110)." (PMID 38351659, 2024).
lupus (3 papers, 2015 to 2022). "AGO2 Abs have been reported in the serum of patients with systemic lupus erythematosus (SLE), scleroderma, Sjögren syndrome (SjS), and other rheumatologic autoimmune diseases." (PMID 36341350, 2022). "In SLE, it was reported that anti-Su autoantibodies, which were usually found in lupus patients, could recognize the catalytic enzyme in miRNA pathways (Ago1, Ago2, Ago3, Ago4 and Dicer), which indicated the possible mutual relationship between miRNA and the pathogenesis of SLE." (PMID 25927578, 2015). "Original studies describing lupus induced by pristane in BALB/c female mice showed prevalence for anti-nRNP/Sm by about 53 to 78% and for anti-Su/Ago2 around 44% to 56%." (PMID 34705865, 2021).
lymph node metastasis (3 papers, 2015 to 2021). "We found that the AGO2 rs3928672 was significantly associated with the advanced lymph node metastasis of NPC." (PMID 26545861, 2015). "In addition, AGO2 over-expression is a risk factor for advanced lymph node metastasis, and it can contribute to malignant behavior in NPC." (PMID 27684719, 2016). "A significantly increased risk of advanced lymph node metastasis of NPC was identified for the AGO2 rs3928672 GA + AA genotype compared with GG genotype in both the Guangxi and Guangdong populations (combined odd ratio = 2.08, 95 % confidence interval = 1.44-3.01, P = 8.60 × 10−5)." (PMID 26545861, 2015). "CRC patients with higher cancer stage (p = 0.009), lymph node metastasis (p = 0.022), and distant metastasis (p < 0.001) exhibited lower AGO2 expression." (PMID 33846300, 2021). "Given the role of AGO2 in the development of NPC, one might expect individuals who carry the rs3928672 A allele, and thus have increased expression of AGO2 over a lifetime, may have a higher risk of developing lymph node metastasis of NPC after establishment of this malignancy." (PMID 26545861, 2015).
nasopharyngeal carcinoma (3 papers, 2015 to 2022). A carcinoma arising from the nasopharyngeal epithelium. "We used three AGO2 specific shRNAs to knock down AGO2 in a human nasopharyngeal carcinoma cell line CNE2Z, and western blots assay confirmed that the protein expression level of AGO2 was remarkably decreased in CNE2Z cells after AGO2 knockdown." (PMID 26545861, 2015). "We examined whether the single nucleotide polymorphisms (SNPs) of AGO2 were related to the risk of nasopharyngeal carcinoma (NPC)." (PMID 26545861, 2015). "First, we expressed HA-tagged RISC components (Ago2, TNRC6A TNRC6B) with or without BGLF2-FLAG in HONE-1 (EBV-negative nasopharyngeal carcinoma) cells and stained the cells for HA and FLAG." (PMID 35007297, 2022).
parasite infection (3 papers, 2017 to 2024). "For example, Ago2-mediated, miRNA-directed RNA silencing has been shown to play a crucial role in host defense against parasitic infection by regulating the expression of immune-related genes and modulating host–pathogen interactions." (PMID 39202383, 2024). "In contrast, the parasite-derived mir-125 was loaded onto Ago-2 only at 12 h timepoint (a time when fhe-miR-125b expression was at its peak) reflecting the changes to the loading of mir-125b as a result of the progression of parasite infection." (PMID 33762636, 2021). "Additionally, Ago2-dependent mechanisms such as miRNA-directed translational repression of target gene expression may influence the replication and dissemination of parasites within the host in an attempt by the host to negate the negative impact of parasite infection." (PMID 39202383, 2024).
sarcoma (3 papers, 2021 to 2024). A usually aggressive malignant neoplasm of the soft tissue or bone. "Moreover, AGO2, EIF4G3, NCBP1, and WDR4 were potential risk factors for DSS in sarcomas." (PMID 36816047, 2023).
status epilepticus (3 papers, 2015 to 2023). Status epilepticus is defined as a continuous seizure lasting more than 30 min, or two or more seizures without full recovery of consciousness between any of them. "We then validated the OA profiling result by individual Taqman miRNA assay and this confirmed miR-22 levels were increased in Ago2-eluted samples exclusively on the contralateral side after status epilepticus." (PMID 26631939, 2015).
triple-negative breast carcinoma (3 papers, 2020 to 2026). An invasive breast carcinoma which is negative for expression of estrogen receptor (ER), progesterone receptor (PR), and human epidermal growth factor receptor 2 (HER2). "Here we report that argonaute 2 (Ago2), a protein with central involvement in RNAi, associates with LASP1 in triple-negative breast cancer (TNBC) cells." (PMID 32872485, 2020). "From all the RBPs investigated, seven were differentially expressed and upregulated (AGO2, EIF4A3, ELAVL1, IGF2BP2/3, LIN28B, and U2AF2), showing that these genes have an important role in triple-negative breast cancer development." (PMID 35805051, 2022).
urothelial carcinoma of the bladder (3 papers, 2017 to 2020). "Despite ongoing research on bladder biomarkers, the clinicopathological impact and diagnostic function of miRNA maturation regulators Drosha and Argonaute proteins AGO1 and AGO2 in urothelial bladder carcinoma remain unclear." (PMID 29857476, 2018). "Similarly, AGO2 was up-regulated in patients with urothelial carcinoma of the bladder, and accumulation of AGO2 implied higher tumor grading and poorer prognosis." (PMID 28903378, 2017).
Wilms tumor (3 papers, 2014 to 2023). An embryonal neoplasm characterized by the presence of epithelial, mesenchymal, and blastema components. "Ago2 mutations have not been identified in Wilms tumors, however, we speculate that Ago2-dependent processing of miR-183/96/182 hairpins might facilitate the increase in miR-183 in Wilms tumors." (PMID 37810246, 2023). "In addition, we conducted AGO2 related RIP assays which revealed circ0093740, miR-136/145 and DNMT3A were all enriched to AGO2 RNA binding protein in both SKNEP1 and G401 Wilms tumor cell lines." (PMID 34168984, 2021).
autoimmune conditions (2 papers, 2006 to 2018). "Autoantibodies targeting microRNA Processing Bodies (PB/GW bodies) have been described broadly in various autoimmune conditions and have been suggested as being potentially complementary biomarkers in PBC patients; these include GW182, Ge-1 and Ago2." (PMID 29554146, 2018).
chronic lymphocytic leukaemia (2 papers, 2020 to 2024). "ts-101 and ts-53 are found in both AGO1 and AGO2 complexes as well as Piwi-L2 complexes in chronic lymphocytic leukemia (CLL), suggesting that they may play similar roles to piRNAs." (PMID 37692525, 2024).
clear cell renal cell carcinoma (2 papers, 2021). "A similar correlation between AGO2 expression and tumorigenesis has been implicated for clear cell renal cell carcinoma." (PMID 33668654, 2021). "The evaluation of mRNA expression data from The Cancer Genome Atlas revealed decreased levels of AGO2 in clear cell renal cell carcinoma tumors as compared to normal tissues." (PMID 33668654, 2021).
Co-infection (2 papers, 2018 to 2023). "Interestingly, we observed a negative effect on ZIKV replication during CHIKV co-infection in the context of Ago2-knockout cells, though his effect was absent during DENV co-infection." (PMID 37440582, 2023).
dengue (2 papers, 2009 to 2023). "have shown that in Anopheles gambiae, ago2 and ago3 are required for defense against O'nyong-nyong virus while ago2, r2d2 and dcr2 are required for anti-dengue defense in Aedes aegypti." (PMID 19763182, 2009).
diabetic cardiomyopathy (2 papers, 2025). Diabetic cardiomyopathy is a disorder of the heart muscle in people with diabetes. "Together, these findings highlight a novel layer of translational regulation in diabetic cardiomyopathy, wherein miRNAs and AGO2 modulate mitochondrial protein synthesis in a target-specific manner." (PMID 40427584, 2025). "In late-stage type II diabetic cardiomyopathy, AGO2 expression was significantly reduced, accompanied by a selective decrease in the translation of mitochondria-encoded proteins, particularly components of the electron transport chain complex III such as CYTB." (PMID 40427584, 2025). "The involvement of subcellular Ago2 in diabetic cardiomyopathy is dual-faceted and can be summarised as follows: First, Ago2 suppresses ATP synthesis by inhibiting the production of mitochondrial ATP synthase subunits." (PMID 40861070, 2025).
endothelial dysfunction (2 papers, 2023 to 2025). In vascular diseases, endothelial dysfunction is a systemic pathological state of the endothelium (the inner lining of blood vessels) and can be broadly defined as an imbalance between vasodilating and vasoconstricting substances produced by (or acting on) the endothelium. "AGO2 and AGO4 are likely to participate in the endothelial dysfunction of children with KD, with AGO4 potentially playing a key role, while AGO1 and AGO3 appear not to participate." (PMID 39857904, 2025). "First, although we demonstrated that Ago2 can ameliorate endothelial dysfunction under diabetic conditions, we did not assess whether Ago2 also exerts a similar effect in other cell types, such as pericyte or neuronal cells." (PMID 36769259, 2023).
esophageal squamous cell carcinoma (2 papers, 2018). Esophageal squamous cell carcinoma (ESCC) is a type of esophageal carcinoma (EC) that can affect any part of the esophagus, but is usually located in the upper or middle third. "Furthermore, Ago2-dependent post-transcriptional regulation of MALAT1 by miR-101 and miR-217 significantly impaired proliferation, migration, and invasion of Esophageal Squamous Cell Carcinoma Cells (ESCC) cells, highlighting the MALAT1-dependent tumor suppressor role of these miRNAs." (PMID 29739426, 2018).
hypopharyngeal carcinoma (2 papers, 2017 to 2021). Carcinoma, predominantly squamous cell, arising from the epithelial cells of the hypopharynx. "The oncogenic function of AGO2 was documented in hypopharyngeal cancer where knock down of AGO2 led to the inhibition of cell growth and tumor formation in mice, as well as activation of the mitogenic FAK/PI3K/AKT pathway." (PMID 33668654, 2021). "In this study, we evaluated the expression level and potential role of AGO2 in the progression of hypopharyngeal carcinoma." (PMID 28903378, 2017). "In this study, we found that knockdown of AGO2 in hypopharyngeal carcinoma cell lines resulted inhibitive effects on cell proliferation in vitro and in vivo." (PMID 28903378, 2017). "To characterize the function of AGO2 in hypopharyngeal carcinoma, we created a cellular model by lentivirus-mediated stable knockdown of AGO2 expression in hypopharyngeal-derived FaDu cell lines." (PMID 28903378, 2017). "While the details about the biological function and molecular mechanism of AGO2 in human hypopharyngeal cancer and the regulatory mechanism about AGO2 on the FAK/PI3K/AKT pathway need to be further investigated." (PMID 28903378, 2017). "All these functions of AGO2 are firstly illuminated in hypopharyngeal cancer, and possibly mediated by FAK/PI3K/AKT pathway." (PMID 28903378, 2017). "In conclusion, AGO2 is overexpressed in hypopharyngeal carcinoma, and up-regulation of AGO2 may be recognized as a valuable indicator for prognostic prediction." (PMID 28903378, 2017). "Here we found the AGO2 expression in hypopharyngeal cancer tissues were generally higher comparing with that of the corresponding adjacent noncancerous epithelium tissues, and these were associated with the more aggressive clinicopathologic features and the poor clinical outcomes." (PMID 28903378, 2017). "Thereby, we hypothesized and partially validated that knockdown of AGO2 retarded cell proliferation and tumor growth possibly through blocking the FAK/PI3K/AKT signaling in hypopharyngeal carcinoma." (PMID 28903378, 2017).
leukaemia (2 papers, 2018 to 2021). "Furthermore, the presence of both AGO1 and AGO2 proteins was essential for the successful induction of differentiation of leukaemia cells upon treatment with retinoic acid or 1,25-dihydroxyvitamin D3, respectively." (PMID 33668654, 2021). "Hence, the biomarker potential of AGO1 and AGO2 in cancers of different origin has been extensively explored, pointing to a prognostic value of AGO proteins in solid tumors as well as leukaemia." (PMID 33668654, 2021).
liver disease (2 papers, 2020 to 2024). "Moreover, further research into the mechanistic role of AGO2 and its autoantibodies in liver disease is imperative to enhance our understanding of disease progression and facilitate the development of novel therapeutic strategies." (PMID 39119295, 2024).
metastatic carcinoma (2 papers, 2024 to 2025). A carcinoma which has spread from the original site of growth to another anatomic site. "Among all types of tissues with breast disease, metastatic carcinomas had the highest levels of plasma membrane-associated Ago2." (PMID 38649663, 2024). "Consistent with the results of cultured cancer cells and tumor xenografts, this increase in EV miRNA-3613-3p in patient plasma was positively correlated with increased Ago2/CAV1 interaction in human metastatic carcinomas." (PMID 38649663, 2024). "CAV-1-AGO2 interactions in the plasma membrane also trigger the sorting and secretion of miR-3613-3p-AGO2-RISC in extracellular vesicles (EVs) in the plasma of metastatic cancer patients." (PMID 40863728, 2025). "In metastatic cancers and carcinomas, CAV1 interaction with AGO2 in the plasma membrane are widely distributed and abundant as compared with primary tumors." (PMID 40863728, 2025).
metastatic disease (2 papers, 2019 to 2024). "Compared with primary tumors, the levels of Ago2 associated with the plasma membrane were substantially higher in 89% of paired metastatic tumors." (PMID 38649663, 2024). "We further evaluated the distribution of Ago2 proteins in paired human breast primary tumors and metastatic tumors." (PMID 38649663, 2024). "We also analyzed the levels of coprecipitated CAV1 by anti-Ago2 antibodies, normalized to the levels of precipitated Ago2, in primary tumors and paired metastatic tumors in the lymph nodes (M) of each patient." (PMID 38649663, 2024). "Compared with primary tumors, the levels of Ago2-bound CAV1 were considerably higher in paired metastatic tumors in 90% of the patients, indicating that metastatic tumors are associated with increased Ago2/CAV1 interaction." (PMID 38649663, 2024). "Therefore, the release of specific miRNAs (e.g., miR-3613-3p) from metastatic tumors in circulation through EVs, facilitated by the increased Ago2/CAV1 interaction in metastatic tumors, can be used as a biomarker of tumor progression." (PMID 38649663, 2024). "In contrast, Ago2 translocated to the plasma membrane of paired metastatic tumors." (PMID 38649663, 2024). "A direct interaction between Ago2 and CAV1, mediated by the positive charge of Ago2 K212, increases the complexity of miRNA actions and modulates exosomal cargo sorting of metastatic tumors." (PMID 38649663, 2024). "Since Ago2/CAV1 interaction increases with human carcinoma progression and metastasis, we also investigated whether EV-mediated miR-3613-3p release increases in the plasma of patients with metastatic tumors." (PMID 38649663, 2024).
oesophageal cancer (2 papers, 2021 to 2022). "To confirm that SBF2-AS1 can be used as a ceRNA to adsorb miR-338-3P and miR-362-3P, we used RNA immunoprecipitation (RIP) to detect whether SBF2-AS1 could bind the AGO2 protein in oesophageal cancer cells." (PMID 33436941, 2021).
oral cancer (2 papers, 2015 to 2020). "To investigate whether silencing of AGO2 in these oral cancer cells altered the expression of miR301a-3p, we collected the cells at 72 hours after AGO2 knockdown, and tested the levels of miR301a-3p." (PMID 31940341, 2020).
renal cell carcinoma (2 papers, 2020 to 2024). "It has been reported that the single-nucleotide polymorphism (SNP) of AGO2 was related to the tumorigenesis of renal cell carcinoma." (PMID 32420319, 2020). "AGO2 was first identified as an oncogene in renal cell carcinoma." (PMID 32420319, 2020).
renal fibrosis (2 papers, 2017 to 2023). A final common manifestation of a wide variety of chronic kidney diseases characterized by glomerulosclerosis and tubulointerstitial fibrosis. "To identify the target genes in renal fibrosis, we performed Ago2-IP with deep sequencing, followed by the examination of putative target protein expression and the luciferase microRNA target assay." (PMID 37333081, 2023).